RPP40 (ribonuclease P/MRP subunit p40)
Description:
Component of ribonuclease P, a ribonucleoprotein complex that generates mature tRNA molecules by cleaving their 5'-ends. Also a component of the MRP ribonuclease complex, which cleaves pre-rRNA sequences.
Synonyms: RNASEP1; bA428J1.3
Tractability: PROTAC: ubiquitination databases record sites on it; its protein half-life has been measured.
Gene: Protein-coding gene on chromosome 6 (4,994,717 to 5,004,063, reverse strand). Ensembl gene ENSG00000124787.
Subcellular location: Nucleus, nucleolus
Subcellular location (Human Protein Atlas): Nucleoplasm
Pathways (Reactome):
Metabolism of RNA: Major pathway of rRNA processing in the nucleolus and cytosol; tRNA processing in the nucleus
Gene Ontology:
Molecular function: protein binding; ribonuclease P activity; ribonuclease P RNA binding; ribonuclease MRP activity
Biological process: tRNA 5'-leader removal; endonucleolytic cleavage in ITS1 to separate SSU-rRNA from 5.8S rRNA and LSU-rRNA from tricistronic rRNA transcript (SSU-rRNA, 5.8S rRNA, LSU-rRNA); RNA processing
Cellular component: multimeric ribonuclease P complex; nucleolar ribonuclease P complex; ribonuclease MRP complex; nucleoplasm; nucleus; nucleolus; ribonuclease P complex
Genetic constraint (gnomAD): Loss-of-function variants: 19 observed, 25.61 expected, observed/expected ratio (o/e) 0.74, 90% interval 0.52 to 1.09. The upper end of that interval is the gene's LOEUF score, 1.09, which puts it in group 4 of 6, group 1 being the genes least tolerant of losing a copy. Missense variants: 283 observed, 306 expected, observed/expected ratio (o/e) 0.92, 90% interval 0.84 to 1.02. Synonymous variants: 128 observed, 121.41 expected, observed/expected ratio (o/e) 1.05, 90% interval 0.91 to 1.22.
Homologues: Orthologues: chimpanzee RPP40 (98% identical), macaque RPP40 (96% identical), guinea pig RPP40 (85% identical), mouse Rpp40 (84% identical), rat Rpp40 (84% identical), pig RPP40 (81% identical), dog RPP40 (79% identical), rabbit RPP40 (76% identical), tropical clawed frog rpp40 (59% identical), zebrafish rpp40 (48% identical).
Diseases named in the same sentence as RPP40 in open-access papers:
RPP40 is named in the same sentence as 9 diseases in open-access papers, as found by Europe PMC text mining. Sharing a sentence is not in itself a finding about the gene and the disease. The quoted sentences say what the papers report.
acute myeloid leukemia (2 papers, 2022 to 2024). Acute myeloid leukemia (AML) is a group of neoplasms arising from precursor cells committed to the myeloid cell-line differentiation. "Moreover, increased levels of RPP40 are implicated in chemoresistance in acute myeloid leukemia and an upregulated expression of RPP40 mRNA predicts recurrence in early-stage triple-negative breast cancer." (PMID 38892733, 2024). "Ribonuclease P/MRP Subunit P40 (RPP40), a component of ribonuclease P and multimeric ribonuclease P complex, was reported as one of the promoting factors for the chemoresistance of acute myeloid leukemia and a recurrence predictor of early-stage triple-negative breast cancer." (PMID 36091104, 2022). "Similarly, RPP40 was also regarded as one of the promoting factors for the chemoresistance of acute myeloid leukemia, and the member of a prognostic signature includes seven mRNAs and could accurately predict the recurrence risks of early-stage triple-negative breast cancer." (PMID 36091104, 2022).
colorectal carcinoma (1 paper, 2025). A malignant epithelial neoplasm that arises from the colon or rectum and invades through the muscularis mucosa into the submucosa. "We engineered the colorectal carcinoma cells HCT116 for dTAG-dependent degradation of RPP40, as above." (PMID 40533478, 2025).
tumor (2 papers, 2022 to 2024). "Therefore, the association analysis between RPP40 expression in tumor cells and the ECM-related gene expressions in CAFs is more convincing." (PMID 36091104, 2022). "RPP40 regulates immune response and the ecto-matrix in tumor microenvironments, suggesting its role in cell proliferation and homeostasis." (PMID 39682314, 2024). "Differential analyses of multiple databases showed that both messenger RNA (mRNA) and the protein expression of RPP40 were significantly upregulated in UCEC tumor tissues." (PMID 36091104, 2022). "As same as the research result from CPTAC samples, immunohistochemical staining results from the HPA database also confirmed that the protein level of RPP40 was markedly upregulated in UCEC tumor tissues." (PMID 36091104, 2022). "RPP40 mRNA expression levels in UCEC tumor tissues (n=91) were significantly upregulated than those in normal tissues (n=12)." (PMID 36091104, 2022). "Paired data analysis showed that the mRNA expression levels of RPP40 in UCEC tumor tissues were significantly upregulated than those in normal endometrial tissues (n=23) according to the TCGA database." (PMID 36091104, 2022). "In the present study, we found that the mRNA expression of RPP40 was significantly upregulated in the tumor tissues of various cancer types, especially in UCEC." (PMID 36091104, 2022). "Moreover, the upregulation of RPP40 was significantly negatively correlated with the tumor infiltration levels of most of immune cell types, such as NK cells, DCs, cytotoxic cells, and CD 8 T cells." (PMID 36091104, 2022). "Furthermore, the protein expression of RPP40 is also significantly upregulated in UCEC tumor tissues." (PMID 36091104, 2022). "In conclusion, the upregulation of RPP40 is significantly correlated with the poor survival and tumor microenvironment of UCEC, suggesting that RPP40 is a promising biomarker of poor prognosis and a potential target of chemotherapy or immunotherapy in UCEC." (PMID 36091104, 2022).
cancer (1 paper, 2022). A tumor composed of atypical neoplastic, often pleomorphic cells that invade other tissues. "However, studies targeting the function of RPP40 in malignant tumors are rarely reported." (PMID 36091104, 2022).
RPP40 also shares sentences with these, for which no sentence is quoted: triple-negative breast carcinoma (2 papers); diabetes (1); leptospirosis (1); systemic sclerosis (1); uterine corpus endometrial carcinoma (1).